Y_RNA (Y RNA )
Gene: Miscellaneous RNA gene on chromosome 11 (93,827,622 to 93,827,734, forward strand). Ensembl gene ENSG00000206911.
Homologues: Orthologues: macaque Y_RNA (99% identical). Paralogues in human: Y_RNA (90% identical), Y_RNA (89% identical), RNY1 (88% identical), Y_RNA (88% identical), Y_RNA (87% identical), Y_RNA (86% identical), RNY1P7 (85% identical), Y_RNA (85% identical), RNY1P11 (84% identical), Y_RNA (84% identical), Y_RNA (83% identical), Y_RNA (82% identical), and 99 more.